BRAF (B-Raf proto-oncogene, serine/threonine kinase)
Diseases named in the same sentence as BRAF in open-access papers (continued):
Sharing a sentence is not in itself a finding about the gene and the disease.
tumor (continued). "Papillary cancer with BRAF mutation was significantly associated with a larger tumor size (P = 0.045), extrathyroidal invasion (P = 0.012), lymph node metastasis (P = 0.008), and a higher TNM stage (P = 0.044)." (PMID 24559116, 2014). "Increased weight, bodyfat percentage, hip, waist and BMI were associated with risk of BRAF wild type tumours (ptrend = 0.007, ptrend = 0.002, ptrend = 0.002, ptrend = 0.001, ptrend = <0.001)." (PMID 24918610, 2014). "The limited activity-selectivity of Sorafenib (BAY 43–9006), the first RAF kinase inhibitor, for the RAF kinases in tumours with BRAF mutation prompted the development of second-generation RAF inhibitors with greater selectivity for mutant BRAF." (PMID 25361007, 2014). "Due to the comparatively small subgroup of male subjects with BRAF-mutated tumours, all analyses were also performed with continuous anthropometric variables, which did not alter the significant associations (data not shown)." (PMID 24918610, 2014). "Targeted sequencing (i.e. codon 599 of BRAF and codons 12 and 13 of KRAS) using a single representative tumor sample from 34/52 (65%) patients revealed a BRAF and KRAS mutation in 2 (6%) and 14 (41%) cases respectively." (PMID 25523272, 2014). "The univariate analysis indicated that the BRAF V600E mutation was associated with age, tumor stage and prognosis (P<0.05)." (PMID 24396464, 2014). "Analysis of plasma from 4 patients identified mutations identical to those found in tumor specimens (BRAF, NRAS, TERT)." (PMID 25516806, 2014). "One tumor harbored a BRAF (D594G) mutation and another with a mutation in NRF2 (G31A), both of which are novel in TSCC, and the mutations have been validated through next-generation target re-sequencing of the same samples (manuscript in preparation)." (PMID 25234657, 2014). "The mutual exclusive occurrence of KRAS and BRAF mutations suggests they occur in different tumor subtypes." (PMID 25367198, 2014). "Because the biopsy revealed that the tumor carried a BRAF V600E mutation, the patient was invited to participate in a double-blind clinical trial in June 2012." (PMID 25228592, 2014). "That is, one patient had a primary tumor that displayed BRAFV600E expression whereas the paired metastasis contained solely BRAF wild-type tumor cells, but harbored a NRAS mutation." (PMID 25526463, 2014). "MYC over-expression was found in 980 (69%) of CRCs and was associated with tumor stage and DNA mismatch repair/BRAF status." (PMID 24503701, 2014). "BRAF: In CRC tumours, BRAF mutations seem to occur more frequently in cases with MSI characterised by deficient DNA mismatch repair (dMMR)." (PMID 25361007, 2014). "We also assayed for mutations in KRAS and BRAF to determine the prevalence of coincident GNAS/KRAS or GNAS/BRAF mutations in our tumor cohort." (PMID 24498230, 2014). "As described, all 13 whole genome analyzed cases harbored mutations or copy number alterations in either NRAS or BRAF (with 1 tumor having both)." (PMID 25393105, 2014). "Nine GNAS mutant tumors (90%) harbored concomitant activating mutations in either the KRAS or BRAF oncogene, which was significantly greater than the mutation frequency of these genes in the tumor population (56%, p<0.0305)." (PMID 24498230, 2014). "Our findings confirm that genetic alterations that occur early in colorectal carcinogenesis, namely mutations in APC, KRAS, NRAS, and BRAF, persist through tumor evolution and show an exceedingly high level of concordance between primary tumor and metastases." (PMID 25164765, 2014). "In patients with conventional PTC, the BRAF V600E mutation was associated with age, tumor stage and prognosis (P<0.05)." (PMID 24396464, 2014).
tumor (continued). "Concurrent screening for the BRAF V600E mutation in tumour DNA from MSI positive cases exhibiting loss of MLH1 and PMS2 expression by IHC, will further assist in the exclusion of non-eligible patients." (PMID 25133505, 2014). "Multivariate analysis indicated that tumor deposits, BRAF mutation and bilobar LM distribution were significantly associated with shorter DFS." (PMID 25162714, 2014). "Several reports have shown that MAPK activation, owing to oncogenic RAS and BRAF mutations, is likely to be involved in promoting cellular invasiveness in different tumour models." (PMID 25361007, 2014). "The discovery that the growth of many tumours is driven by a specific mutation in the BRAF oncogene, i.e., BRAF(V600E), has led to the development of the RAF inhibitors vemurafenib and dabrafenib." (PMID 24651269, 2014). "The BRAF V600E mutation has been described as a predictor of tumor aggressiveness in metastatic disease and also of low RRs to cetuximab and panitumumab." (PMID 24811491, 2014). "From a biologic perspective, this finding supports the notion that the poor outcome of tumours with BRAF mutation is shared with some non-BRAF-mutated tumours, suggesting that they have common biology driving poor survival after relapse." (PMID 25361007, 2014). "Patients with BRAF-mutation positive tumours and BRAF wildtype tumours had comparable irDCRs (38% vs 39%), as did patients with or without NRAS mutations (57% vs 49%)." (PMID 24885479, 2014). "KRAS and BRAF mutations were analysed by pyrosequencing in tumours from 494 incident CRC cases in the Malmö Diet and Cancer Study." (PMID 24918610, 2014). "Overall, our results indicate that ARMS-PCR is more sensitive than automated dideoxy sequencing in detecting low BRAF V600E allele burdens in FFPE tumor specimen." (PMID 24252159, 2013). "Acquired mutations of BRAF have been described in several tumour types and while BRAF mutations undoubtedly contribute to malignant proliferative processes, the heterogeneity of tumour types implicates further cell lineage-specific pathogenic events." (PMID 23653869, 2013). "In MSS tumours, BRAF mutation was significantly associated with a reduced CSS in unadjusted analysis, and was borderline significant in adjusted analysis." (PMID 24020794, 2013). "These patients would be likely to benefit from adjuvant targeted therapy, with the degree of benefit depending on how early the BRAF mutation had occurred during the cellular evolution of the secondary tumor." (PMID 23951556, 2013). "High-level MSI (MSI-H) comprises 15% of sporadic CRC, and these are positively correlated with patients being female, over 60 years of age, having BRAF mutations and being right-sided tumours." (PMID 23356214, 2013). "These two cases illustrate the importance of high assay sensitivity of our ARMS-PCR assay to detect low BRAF V600E allele burdens in tumor samples." (PMID 24252159, 2013). "At univariate analysis, in the present cohort of patients treated with cetuximab the presence of BRAF mutations was significantly associated with an 8.1-fold increased risk of death compared to patients harbouring BRAF-wild type tumours." (PMID 23374602, 2013). "BRAF mutation has been associated with the serrated pathway of tumour development, and these tumours tend to be in groups 1 and 2 of the Jass classification." (PMID 23356214, 2013). "In men, BRAF mutation was an independent factor of poor prognosis in MSS tumours (unadjusted HR = 3.46, 95% CI = 1.78–6.74; adjusted HR = 4.91, 95% CI = 1.99–12.12)." (PMID 24020794, 2013). "PTEN analysis using the validated IHC assay, along with testing for MSI, PIK3CA, and BRAF mutations, are among the correlative studies that will be performed on tumor specimens from patients treated in this study." (PMID 24156022, 2013).
tumor (continued). "KRAS mutations were detected in 72 tumours (31.9%), mostly in exon 2, in codon 12 in 45 cases (20.0%) and in codon 13 in 16 cases (7.0%), while BRAF V600E mutations were found in 6 cases (2.6%)." (PMID 23374602, 2013). "Nosho et al3 verified these categories, also validating the finding that CIMP-high tumours were predominantly poorly differentiated, proximally located, microsatellite unstable and frequently had BRAF mutations." (PMID 23096130, 2013). "The tumor staging (T or N stage, tumor grade) had a lesser impact on the prognostic value of the BRAF mutation status, while the tumor background (site and microsatellite (in)stability) significantly influenced the prognostic." (PMID 24073892, 2013). "A shifted termination assay (STA) fragment analysis was used to detect common V600 BRAF mutations in 159 PTCs with DNAs extracted from formalin-fixed paraffin-embedded tumor tissue." (PMID 23883275, 2013). "BRAF mutations are also found in 40 to 70% of papillary or anaplastic thyroid cancers and in small percentages of many other types of tumor." (PMID 23555633, 2013). "In conclusion, we present the first patient with GIST and a V600E BRAF mutation whose tumor showed regression while receiving treatment with a BRAF inhibitor." (PMID 23470635, 2013). "The detection of KRAS and BRAF mutations analysis was performed in 94 and 83 tumor tissues, respectively." (PMID 23637996, 2013). "Tumors were tested for MEIS1 promoter methylation status (n = 228), MSI status (n = 213), BRAF mutation status (n = 163) and tumor location (n = 168)." (PMID 24244575, 2013). "Our results indicate that ARMS-PCR is more sensitive than automated dideoxy sequencing in detecting low BRAF V600E allele burdens in FFPE tumor specimen." (PMID 24252159, 2013). "Recently, systematic review and meta-analyses on PTC showed that BRAF mutation is significantly associated with recurrence, lymph node metastasis, extrathyroidal extension and advanced tumor stages." (PMID 23883275, 2013). "KRAS codons 12 and 13, and BRAF mutations were analysed by pyrosequencing of tumours from 525 and 524 incident CRC cases in The Malmö Diet and Cancer Study." (PMID 24020794, 2013). "Subtype D was not significantly enriched for any of the tested variables except for the BRAF mutated signature and possibly represents a mixture of tumours that have the EMT/stroma signature in common." (PMID 23836465, 2013). "We identified 758 regions with a BRAF mutation-specific methylation change, of which 96% had a higher tumor/normal methylation ratio in the BRAF mutant group." (PMID 23324568, 2013). "The adverse prognostic effect of PIK3CA mutation on survival was restricted to patients with a wild-type BRAF mutated tumor." (PMID 23785428, 2013). "RNA knockout and compound inhibition of BRAF causes cell cycle arrest and death of mutant BRAF tumor cells, mitigating the clinical use of BRAF inhibitors for treatment of activated BRAF-driven cancers." (PMID 23844038, 2013). "Further, 446 (85.1%) of the tumours were BRAF wild-type, 76 (14.5%) were BRAF V600E-mutated and 2 (0.4%) were BRAF K601E-mutated with a total of 78 (14.9%) cases harbouring a BRAF mutation." (PMID 24020794, 2013). "BRAF p.V600E mutations were only studied in two patients, and were detected in both cases, including the tumor DNA obtained from one thymic sample." (PMID 23813854, 2013). "In half of the discrepant cases, we found a wild-type primary tumor and a mutated metastasis (78% BRAF and 22% NRAS)." (PMID 23987572, 2013). "Clustering analyses based on selected miRNAs suggest preliminary signatures characteristic of clinical response to combination treatment and of tumor BRAF mutational status." (PMID 24047116, 2013).
tumor (continued). "These BRAF mutations constitutively activate BRAF and its downstream signaling of the Mitogen-Activated Protein -kinase pathway promoting proliferation, survival and spreading of tumor cells." (PMID 23976959, 2013). "Yamauchi et al13 recently carried out a study which examined the rates of CIMP, KRAS and BRAF mutations and microsatellite instabilities (MSIs) compared to the location of tumours in the colon or rectum." (PMID 23096130, 2013). "The differences in the published LOD for the three test methodologies were clearly highlighted when testing artificial tumor blends with 5% mutant BRAF alleles." (PMID 23326492, 2013). "As BRAF mutations influence tumor growth, it is unlikely that they would confer metastatic capability." (PMID 23951556, 2013). "We found an association between PIK3CA mutation and poor overall survival for patients with a BRAF wild-type tumor." (PMID 23785428, 2013). "BRAF mutation was overall associated with a significantly shorter CSS in patients with MSS tumours in unadjusted analysis (HR = 2.36; 95% CI = 1.44–3.86) and borderline significant in adjusted analysis (HR = 1.80; 95% CI = 0.98–3.28)." (PMID 24020794, 2013). "To investigate this association, we compared the tumor/normal methylation ratio profiles of BRAF wildtypes (n = 11) with those containing the BRAFV600E mutation (n = 8)." (PMID 23324568, 2013). "In these tumor cells glycolysis was shown to be driven by mutated BRAF activity, resulting to addiction to this oncogene." (PMID 24334291, 2013). "Mutations within tumors can play a role in this process; BRAF mutations drive tumor cells to produce pro-inflammatory cytokines like VEGF, IL-10, and IL-6, while at the same time decreasing expression of anti-tumor cytokines such as IL-12." (PMID 24829749, 2013). "In men with MSS tumours, BRAF mutation was an independent factor of poor prognosis (HR = 4.91; 95% CI = 1.99–12.12)." (PMID 24020794, 2013). "After restricting the analysis to patients with a BRAF wild-type tumor, PIK3CA mutation was significantly associated with poorer overall survival (HR 1.51, 95% CI 1.04–2.19, P = 0.03) compared with wild-type PIK3CA." (PMID 23785428, 2013). "KRAS mutation analysis in codons 12 and 13 was performed in the tumor tissue of 94/150 patients, and BRAF mutation analysis in codon 600 was performed in 83/150 cases." (PMID 23637996, 2013). "Vasculature was dramatically compromised, with similar extent, in mutated and wild type BRAF xenografts, and most likely this event contributed to determine the dramatic inhibition of tumor growth observed in treated xenografts of both types." (PMID 24238212, 2013). "In the present study, although the numbers of cases are small, we found that BRAF mutation was significantly associated with extrathyroidal extension and advanced tumor stages using the FFPE PTC tissue samples and standard method to detect BRAF mutations." (PMID 23883275, 2013). "Tumour DNA was pyrosequenced for KRASc.146, BRAF, NRAS, and PIK3CA mutations, and predefined molecular subgroups were analysed for interaction with the effect of panitumumab." (PMID 23725851, 2013). "We found that 10/18 (56%) patients had tumor specimens that were concordant for the BRAF mutation; that is, both their primary and metastatic specimens had a mutant BRAF allele." (PMID 22235286, 2012). "PLX4720 causes cell-cycle arrest, apoptosis, and tumor growth delays in BRAF mutant tumor xenograft models." (PMID 22792460, 2012). "The two tumours that presented a BRAF or NRAS mutation also presented the ATF1-EWS fusion gene and were considered atypical." (PMID 22693489, 2012). "Genetic data suggests that mutations in Ras and BRAF oncogenes are somewhat equivalent during the early stages of tumor development." (PMID 22869096, 2012).
tumor (continued). "Although the larger cluster of 47 samples (Cluster-Group 1; open squares) consisted of 26 (55%) KRAS/BRAF wild-type tumors, KRAS/BRAF wild-type and mutated cases were equally distributed within the two tumor clusters (P = 0.17)." (PMID 23226389, 2012). "Recently, a monoclonal antibody (antibody VE1) which reliably detects BRAF V600E mutated protein in formalin-fixed and paraffin-embedded tumor tissue samples has been generated." (PMID 22385786, 2012). "If the tumor is dMMR, then follow-up tests including BRAF mutation and genetic testing will identify patients with HNPCC." (PMID 22792460, 2012). "Among patients with MSS/MSI-L tumors, methylation was still associated with right-sided disease (p = 0.0125), higher-tumor grade (p < 0.0001), lymph node positivity (p = 0.0207), and BRAF mutation (p < 0.0001." (PMID 22925370, 2012). "Tumours from a subset of patients were also evaluated for BRAF, NRAS, and c-Kit mutations as a potential biomarker of response." (PMID 22127285, 2012). "Among available DNA samples, 384 primary tumours were also evaluated for occurrence of BRAF (in exon 15) and PIK3CA (in exons 9 and 20) mutations." (PMID 22931052, 2012). "Based on the generated phosphosubstrate profiles, a binary class partition model discriminated correctly between tumor KRAS/BRAF wild-type and mutation status in 67% of cases." (PMID 23226389, 2012). "If the tumor is BRAF wild type, we then perform gene mutation analysis to separate the tumors with germ line mutation from tumors that have MSI phenotype due to hMLH1 methylation and are BRAF wild type." (PMID 22792460, 2012). "In this paper, we describe a novel KIAA1549:BRAF fusion transcript in a sporadic PA tumor associated with increased ERK activation and review the spectrum of BRAF genetic alterations in this common pediatric low-grade central nervous system neoplasm." (PMID 22548077, 2012). "In the current study, we analyzed a large number of primary and metastatic melanoma tumor specimens for BRAF intra- and inter-tumor heterogeneity using a combination of 3 different BRAF mutation-detection assays as well as laser-capture microdissection." (PMID 22235286, 2012). "We found evidence for both intra- and inter-tumor heterogeneity of BRAF mutations within and among multiple tumors from individual patients." (PMID 22235286, 2012). "The two tumours which were found to harbor mutations in the BRAF and NRAS gene also presented the ATF1-EWS fusion gene and were considered atypical." (PMID 22693489, 2012). "Two studies utilizing more sensitive genetic approaches have reported higher rates of BRAF mutation and confirmed that the mutation can be limited to select areas within a tumor." (PMID 22808163, 2012). "BRAF mutation leads to a constitutive activation of mitogen activated protein kinase pathway which is essential for cell proliferation and tumor progression." (PMID 23056577, 2012). "In the present study, binary supervised classification analysis of the ex vivo-generated phosphopeptide profiles discriminated correctly between tumor KRAS/BRAF wild-type and mutated samples in two-thirds of cases." (PMID 23226389, 2012). "Whilst none of the three EGFR array peptides was found among phosphosubstrates distinguishing tumor KRAS/BRAF mutation status at group level, all of the three peptides representing ERBB2 and ERBB4 were among the discriminating substrates." (PMID 23226389, 2012). "Of the KRAS wild-type patients, 4 had a BRAF mutated tumour (1 good responder and 3 poor responders)." (PMID 22804917, 2012). "A small number of genes are recurrently mutated in TGCT, including KIT, KRAS2 and BRAF, but in each case these represent <10% of tumours analysed." (PMID 23068969, 2012). "In this pathway, PIK3CA, KRAS and BRAF genes are frequently activated by mutations in various tumour types, including CRC with frequencies of 10–30%, 30–40% and 5–22%, respectively." (PMID 21673680, 2011).